MIR5194 (microRNA 5194)
Synonyms: hsa-mir-5194; mir-5194
Gene: MicroRNA gene on chromosome 8 (130,008,334 to 130,008,453, reverse strand). Ensembl gene ENSG00000264653.
Homologues: Orthologues: chimpanzee MIR5194 (100% identical).